GJA1 (gap junction protein alpha 1)
Diseases named in the same sentence as GJA1 in open-access papers (continued):
Sharing a sentence is not in itself a finding about the gene and the disease.
Cirrhosis (5 papers, 2013 to 2026). A chronic disorder of the liver in which liver tissue becomes scarred and is partially replaced by regenerative nodules and fibrotic tissue resulting in loss of liver function. "Taken together, these results indicated that GJA1 transcription was enhanced in HCCs, hepatic cirrhosis, and pulmonary metastases from HCCs, but diminished in portal vein tumor thrombus metastasis from HCCs, compared to their relative controls." (PMID 34693020, 2021). "The expression of GJA1 was significantly increased in HCCs and hepatic cirrhosis compared to that in NTs." (PMID 34693020, 2021). "GJA1 showed consistent upregulation in both experimental models and human cirrhosis." (PMID 41699670, 2026). "Because the functional relevance of GJA1 in HCCs and hepatic cirrhosis remains unknown, we analyzed GJA1 mRNA expression with 13 public datasets." (PMID 34693020, 2021). "GJA1 also mediates hepatic cirrhosis and metastasis of several malignancies." (PMID 34693020, 2021). "In the current study, we used public datasets to compare GJA1 expression between HCCs and adjacent nontumor tissues (NTs), between hepatic cirrhosis and NTs, as well as between metastatic HCCs and HCCs without metastasis." (PMID 34693020, 2021).
colitis (5 papers, 2020 to 2025). Inflammation of the colon. "Bifidobacterium breve UCC2003 was shown to increase and mucus layer generation genes including Muc2, Muc6, Muc5c, and Muc4 and Gja1 and Gjb8 in the mucosa-associated with DSS colitis." (PMID 39849930, 2024). "Gja1 plays a role in the innate immune control of commensal-mediated wound repair of IECs, although enteric glial Gja1 does not affect acute DSS-induced colitis." (PMID 38891118, 2024).
invasive ductal carcinoma (5 papers, 2016 to 2022). "For validation, the feature and spatial feature plots of MAF, CD248, GJA1, LAMA3, TJP1, LAMC2, and COL17A1 demonstrated to show the location in BRCA samples, and they were highly-expressed in the invasive ductal carcinoma tissue (cluster 2, 4, 7, 9, 12)." (PMID 33585235, 2020).
metabolic syndrome (5 papers, 2022 to 2025). A cluster of metabolic risk factors for CARDIOVASCULAR DISEASES and TYPE 2 DIABETES MELLITUS. "We propose that the less severe metabolic syndrome developing in Gja1-ablated mice overrides a poorer glucose tolerance caused by loss of Cx43 in the mitochondria of mature adipocytes, thus limiting the impact of high-calorie intake on energy metabolism." (PMID 38349739, 2024). "Gja1 ablation in mesenchymal lineage cells is partially protective against HFD-induced metabolic syndrome and fat accumulation." (PMID 38349739, 2024).
pancreatic ductal adenocarcinoma (5 papers, 2017 to 2025). An infiltrating adenocarcinoma that arises from the epithelial cells of the pancreas. "In addition, it was found that exosomal miR-30b-5p derived from hypoxic pancreatic ductal adenocarcinoma cells regulated the expression of gap junction protein GJA1 in endothelial cells and promoted angiogenesis through miR-30b-5p/GJA1 axis." (PMID 39928285, 2025).
sudden infant death syndrome (5 papers, 2013 to 2023). Unexpected death in infancy which remains unexplained following autopsy, review of the medical history, and investigation of the death circumstances and death scene. "Notably, a GJA1 gene mutation (p.Glu42Lys) leads to sudden infant death syndrome (SIDS) without cardiac malformations." (PMID 35457072, 2022).
colon adenocarcinoma (4 papers, 2011 to 2023). "Thus, the rate of mutated GJA1 gene (coding Cx43) is increased in colon adenocarcinomas, stomach adenocarcinomas and cutaneous melanoma." (PMID 36829482, 2023).
congenital heart disease (4 papers, 2013 to 2022). "The association of GJA1 with laterality defects or congenital heart disease remains unsure." (PMID 35547246, 2022).
cystitis (4 papers, 2014 to 2022). Inflammation of the urinary bladder. "In this study, we revealed that GJA1 up-regulation resulted in changes in voiding behavior of the cystitis model mice through gap junction formation in the smooth muscle layer, indicating that molecular changes in bladder inflammation affected bladder storage function." (PMID 25099633, 2014). "Therefore, GJA1 up-regulation might activate those mechanisms in urothelium or suburothelium, contributing to the etiology of our cystitis model." (PMID 25099633, 2014).
Hyperkeratosis (4 papers, 2019 to 2024). Hyperkeratosis is a histopathological term defining a thickened stratum corneum and may be present in many different skin conditions, with many possible overlaps. "Various skin abnormalities, such as hyperkeratosis, abnormality of the plantar skin of the foot, palmoplantar keratoderma, subcutaneous nodules and erythema, were associated with GJA1, KRT1, KRT2, PSEN1 and INSR." (PMID 37185447, 2023). "Of the non-syndromic conditions identified by mutations in GJA1, both EKVP and PPKCA1 share a hyperkeratosis phenotype, whereas ILVEN affects Blaschko’s lines (discussed further in Section 2.4)." (PMID 31817921, 2019).
hypotrichosis (4 papers, 2019 to 2025). A congenital condition, usually due to genetic aberrations, that is characterized by a lack of hair growth on the head and/or body. "Most research on GJA1 has focused on human dermatological disorders, such as hypotrichosis (a skin disease characterized by hair loss) and curly hair." (PMID 40369759, 2025). "Additionally, a recently discovered GJA1 mutation (Cx43-G38E) results in a new non-syndromic phenotype whose mechanism is also not fully understood, known as Hypotrichosis with Keratosis Follicular and Hyperostosis." (PMID 31817921, 2019).
inflammatory bowel disease (4 papers, 2021 to 2025). A spectrum of small and large bowel inflammatory diseases of unknown etiology. "Gja1 has been thought to be involved in the pathophysiology of a variety of intestinal epithelial (IEC) barrier diseases, including inflammatory bowel diseases, necrotizing enterocolitis, and enteric infection." (PMID 36809593, 2023).
Insulin resistance (4 papers, 2023 to 2025). Increased resistance towards insulin, that is, diminished effectiveness of insulin in reducing blood glucose levels. "In the subcutaneous adipose tissue depot, gene expression of DSP and GJA1 was negatively correlated with Homeostatic Model Assessment for Insulin Resistance (HOMA-IR), indicating at a potential role in insulin sensitivity." (PMID 41275133, 2025). "Partial protection from HFD-induced glucose intolerance and insulin resistance, exactly as we report here, and reduced diet-induced inflammation in gonadal adipose tissue has been observed in mice with selective Gja1 ablation in macrophages." (PMID 38349739, 2024). "GJA1 was found interacting with a suppressor of cytokine signaling 3 (SOCS3) and other proteins involved in the mechanism leading to tumor progression through insulin resistance-related pathways." (PMID 37529379, 2023).
ischemia reperfusion injury (4 papers, 2015 to 2021). Adverse functional, metabolic, or structural changes in ischemic tissues resulting from the restoration of blood flow to the tissue (reperfusion), including swelling; hemorrhage; necrosis; and damage from free radicals. "We find that GJA1-20k-induced smaller mitochondria have decreased reactive oxygen species (ROS) generation and, in hearts, provide potent protection against ischemia-reperfusion injury." (PMID 34608863, 2021).
keratitis (4 papers, 2017 to 2021). A corneal disease that is characterized by inflammation of the cornea. "Mutations in GJB2, GJB6, and GJA1 result in keratitis, corneal opacity, skin disorders, and hearing loss." (PMID 34381080, 2021).
lung neoplasm (4 papers, 2011 to 2024). A benign or malignant, primary or metastatic neoplasm involving the lungs. "Overall from previous and current tumor analyses using different dosing regimens, carcinogens, and strains of mice, a panel of common transcripts (e.g. Arg1, Areg, Ereg, Ccr2, Cdkn1a, Gja1, Ptgis, Spp1) may provide a useful tool for early diagnosis of lung neoplasm." (PMID 22039513, 2011).
microphthalmia (4 papers, 2020 to 2025). Congenital or developmental anomaly in which the eyeballs are abnormally small. "Mutations most commonly affect the extracellular-1 and cytoplasmic-1 domains of connexin-43 (gene product of GJA1), predominately manifesting in microphthalmia and microcornea." (PMID 32318302, 2020). "Interestingly, genes involved in microphthalmia (VAX1, ALDH1A3, GJA1, and SMOC1) and retinal dystrophies (ADAMTS9, KCNJ13, CA2 and ABCA4) were also selected." (PMID 37479765, 2023).
polycystic ovarian syndrome (4 papers, 2020 to 2025). "Among these, two downregulated genes have previously been associated with premature ovarian insufficiency (POI): Gja1, which is essential for oocyte–cumulus communication and implicated in polycystic ovarian syndrome, and Hif1a, a regulator of follicular development via hypoxia pathways." (PMID 41278955, 2025). "Androstenedione may play a role in the expression level of GJA1 both in rat polycystic ovary." (PMID 32190671, 2020).
benign prostatic hyperplasia (3 papers, 2016 to 2020). A non-cancerous nodular enlargement of the prostate gland. "GJA1 (also known as connexin 43) expression was measured to be significantly reduced in tumor tissues compared to that of benign prostatic hyperplasia." (PMID 32953881, 2020).
COVID-19 (3 papers, 2022 to 2026). A disease caused by infection with severe acute respiratory syndrome coronavirus 2. "Our results suggest that the increase in tissue expression of GJA-1 in the COVID-19 group may play a role in forming new vessels, contributing to the angiogenic response in the hypoxemic and pro-inflammatory environment." (PMID 36992415, 2023). "The increased expression of TNF-α, NF-kB, VEGF, VEGFR-1, GJA-1 (Connexin-43), and CTNNB-1 (β-catenin) in the COVID-19 group suggests a strong activation of angiogenic pathways in response to hypoxia and hyperinflammation associated with SARS-CoV-2 infection." (PMID 36992415, 2023).
craniometaphyseal dysplasia (3 papers, 2017 to 2022). Craniometaphyseal dysplasia (CMD) is a very rare genetic bone disease characterized by progressive diffuse hyperostosis of cranial bones causing facial dysmorphism and functional repercussions, and metaphyseal widening of long bones. "Craniometaphyseal dysplasia has been linked to heterozygous mutations in ANKH (MIM# 123000) and biallelic mutations in GJA1 (MIM# 218400)." (PMID 35096710, 2021).
dementia (3 papers, 2014 to 2020). Loss of intellectual abilities interfering with an individual's social and occupational functions. "Similar results were observed in the ROSMAP RNA-seq dataset, suggesting that the mRNA expression of GJA1 is associated with AD pathogenesis and dementia." (PMID 30577786, 2018).
Erythema (3 papers, 2019 to 2023). Redness of the skin, caused by hyperemia of the capillaries in the lower layers of the skin. "These heterozygous mutations in GJA1 cause a consistent clinical phenotype of normal skin at birth which develops symmetrical erythematous on the hands and feet at age of 1–10 months, with progression to keratotic erythema, plaques." (PMID 30924322, 2019).
focal epilepsy (3 papers, 2018 to 2020). A seizure caused by a localized disorder. "Some syndrome-specific associations were detected, such as the relatively strong signal for STX1B in JME, and the association of GJA1 with focal epilepsy-hippocampal sclerosis." (PMID 30531953, 2018). "Prioritized genes associated with focal epilepsy with hippocampal sclerosis include the gap-junction gene GJA1." (PMID 30531953, 2018).
HCMV infection (3 papers, 2018 to 2021). "Of these proteins, 12 were rescued at 12 hr post infection, including connexin family gap junction protein alpha 1 (GJA1), which has previously been reported to be degraded during HCMV infection." (PMID 30122656, 2018).
hyperostosis (3 papers, 2019 to 2023). Excessive thickening of bone. "Hyperostosis, abnormalities of odontoid tissue and carious teeth are problems related to bone or hard tissues, and these were associated with common proteins, such as GJA1 and SLC24A4." (PMID 37185447, 2023).
hypoplastic left heart syndrome (3 papers, 2019 to 2023). Hypoplastic left heart syndrome (HLHS) refers to the abnormal development of the left-sided cardiac structures, resulting in obstruction to blood flow from the left ventricular outflow tract. "Mutations in the gene for Cx43 (GJA1) were found to cause a hypoplastic left-heart syndrome." (PMID 30781714, 2019). "GJA1 gene mutations, which cause heart disease, often correspond with cardiac malformations (e.g., ventricular septal defect [VSD], atrioventricular septal defect [AVSD], and hypoplastic left heart syndrome [HLHS]) in mainly autosomal recessive inheritance." (PMID 35457072, 2022).
lentivirus infection (3 papers, 2021 to 2022). Virus diseases caused by the Lentivirus genus. "Overexpression of GJA1 by lentivirus infection promoted proliferation and migration, while conditioned medium from HSCs overexpressing GJA1 promoted migration but inhibited proliferation of Hep3B and PLC-PRF-5 cells." (PMID 34693020, 2021).
myotonic dystrophy (3 papers, 2017 to 2018). An inherited progressive disorder affecting the muscles. "In myotonic dystrophy patients, miR-1 loss is predicted to cause upregulation of its target genes such as GJA1 (Connexin 43) and CACNA1C (Cav 1.2), leading to dysregulation of important gap junction and calcium channel proteins in the heart." (PMID 30057901, 2018).
ventricular septal defect (3 papers, 2020 to 2022). The presence of a defect (opening) in the septum that separates the two ventricles of the heart. "The expression level of miR-1-1 is decreased in patients with ventricular septal defects and is associated with a rise in the expression level of the gap junction protein alpha 1 (GJA1) and SOX9 proteins." (PMID 32952941, 2020).
alopecia (2 papers, 2022 to 2023). Hair loss usually from the scalp. "Connexin 43 (Cx43), encoded by GJA1, is a connexin expressed in both the skin and heart, and variants in GJA1 are known to cause a broad range of phenotypes, including PPK, alopecia and cardiac conductive disorders thus capable of causing a cardiocutaneous phenotype." (PMID 36142674, 2022).
endometrial adenocarcinoma (2 papers, 2013 to 2014). "In addition it has been found that the expression of GJA1 decreases with increased grade of endometrial adenocarcinoma." (PMID 23675859, 2013). "In addition it was found that the expression of GJA1 decreases with increased grade of endometrial adenocarcinoma." (PMID 23675859, 2013).
nasopharyngeal carcinoma (2 papers, 2014 to 2016). A carcinoma arising from the nasopharyngeal epithelium. "Similarly, downregulation of Cx43 in nasopharyngeal carcinoma CNE-1 cells was found to be associated with GJA1 (Cx43) gene hypermethylation." (PMID 25018732, 2014).
primary lymphedema (2 papers, 2017 to 2025). A congenital condition that results in swelling in the arms or legs, and can occur during adolescence or adulthood. "Mutations in the genes encoding FOXC2, (FOXC2) CX47 (GJC2), and CX43 (GJA1) cause primary lymphedema in man." (PMID 28724617, 2017).
renal carcinoma (2 papers, 2019 to 2024). A carcinoma arising from the epithelium of the renal parenchyma or the renal pelvis. "Cell experiments confirmed the inhibitory effects of increased GJA1 expression on the migratory capacity of human renal cancer (RCC) cell lines." (PMID 38792963, 2024). "Our studies revealed that GJA1 holds diagnostic significance across various cancer types and can serve as a standalone favorable prognostic biomarker for KIRC, and increased GJA1 expression led to the inhibition of the migration capacity of renal cancer cells." (PMID 38792963, 2024). "Cell experiments confirmed the inhibitory effects of increased GJA1 expression on the migratory capacity of human renal cancer (RCC) cell lines, and protein–protein interaction (PPI) analysis predicted that CDH1 and CTNNB1 were closely related to Cx43." (PMID 38792963, 2024).
renal hypertension (2 papers, 2016). Hypertension caused by the kidney's hormonal response to narrowing or occlusion of the renal arteries. "Seven of them (Agtr1a, Fn1, Gja1, Lama2, Mmp2, Mmp9, Nos3) are known as being associated with renal hypertension." (PMID 28105926, 2016). "Six of these genes (Ace, Cyp2j4, Gja1, Mmp9, Ppara, and Ren) were described as genes associated with renal hypertension." (PMID 26821914, 2016). "The changes in expression of DEGs associated with renal hypertension (Agtr1a, Fn1, Gja1, Lama2, Mmp2, Mmp9, Nos3) may also be suggested to have a significant impact on disease development in ISIAH rats." (PMID 28105926, 2016).
sensorineural hearing loss (2 papers, 2010 to 2024). "In addition, the mutations identified in GJA1 that were associated with sensorineural hearing loss may actually be located in a pseudogene of the connexin 43-encoding GJA1 gene, on chromosome 5." (PMID 20668687, 2010).
syndactyly (2 papers, 2013 to 2019). A disease characterized by the presence of syndactyly, including syndromic and non-syndromic forms. "Mutations of GJA1 lead to loss of the functional activity of CX43, which in turn leads to reduced BMPs and syndactyly (Syndactyly type 3, OMIM 186100)." (PMID 31637260, 2019).
asplenia (1 paper, 2021). "This included genes associated with asplenia i.e. GJA1, HMOX1, RPSA, STIM1 and AIRE." (PMID 34781974, 2021). "GJA1, HMOX1 and RPSA, have been described as defective in isolated congenital asplenia." (PMID 34781974, 2021).
Autoimmunity (1 paper, 2022). The occurrence of an immune reaction against the organism's own cells or tissues. "Gja1 encodes connexin 43, which is important for gap junctions between KCs and is targeted by pemphigus autoimmunity." (PMID 35870560, 2022).
bone metastasis (1 paper, 2022). Transfer of a neoplasm from its primary site to bones. "In the validation dataset of GSE14020, GJA1, IGFBP6, ITGBL1, SLC44A1, and TGFBI expressions in the bone-metastasis group were different from those in the control group." (PMID 36046013, 2022).
cardiocutaneous syndrome (1 paper, 2022). "The reported variants associated with cardiocutaneous syndrome, in genes DSP, JUP, DSC2, KLHL24, GJA1, are classified by interpretation guidelines from the American College of Medical Genetics and Genomics." (PMID 36142674, 2022).
cerebral microbleeds (1 paper, 2020). Cerebral microbleeds are a group of pathological processes affecting the small arteries, arterioles, capillaries and venules of the brain, as detected by brain imaging techniques. "Association of GJA1 gene SNPs and cerebral microbleeds (multivariable analysis)." (PMID 33324328, 2020).
epidermal disease (1 paper, 2024). A skin disease that involves the epidermis. "In addition to Cx26, mutations in GJB6, GJB4, GJB3 and GJA1, encoding Cx30, Cx30.3, Cx31 and Cx43, respectively have also been linked to diverse epidermal diseases." (PMID 38827992, 2024).
Holt-Oram syndrome (1 paper, 2024). Holt-Oram syndrome (HOS) is the most common form of heart-hand syndrome and is characterized by skeletal abnormalities of the upper limbs and mild-to-severe congenital cardiac defects. "Holt-Oram syndrome is partially caused by variants in the TBX5 gene, and GWAS studies on AF have shown several significant loci with nearest genes known to be important for heart development and causal for CHD, such as NKX2-5, GATA4, GJA1, and GJA5." (PMID 38454350, 2024).
lymphatic disorders (1 paper, 2021). "Whether we will be able to target Cxs for the treatment of lymphatic disorders will very much depend on the unraveling of the effects of the GJC2 and GJA1 gene mutations (and maybe in the future also GJA4 and Panx1 gene mutations) in relevant in vitro, ex vivo and in vivo models." (PMID 34072103, 2021).